CFAP46 (cilia and flagella associated protein 46)
Description:
As part of the central apparatus of the cilium axoneme plays a role in cilium movement.
Synonyms: C10orf123; C10orf124; C10orf92; C10orf93; TTC40; DKFZp434A1721; bA288G11.4; bA288G11.5; bB137A17.2; FLJ25954; bB137A17.3
Tractability: No criterion of Open Targets' tractability assessment is met for any kind of drug.
Gene: Protein-coding gene on chromosome 10 (132,808,392 to 132,942,823, reverse strand). Ensembl gene ENSG00000171811.
Subcellular location: Cytoplasm, cytoskeleton, cilium axoneme
Subcellular location (Human Protein Atlas): Annulus; Mid piece; Principal piece
Gene Ontology:
Biological process: axoneme assembly; cilium movement involved in cell motility
Cellular component: axoneme
Genetic constraint (gnomAD): Loss-of-function variants: 238 observed, 298.24 expected, observed/expected ratio (o/e) 0.8, 90% interval 0.72 to 0.89. The upper end of that interval is the gene's LOEUF score, 0.89, which puts it in group 3 of 6, group 1 being the genes least tolerant of losing a copy. Missense variants: 3,270 observed, 3,438 expected, observed/expected ratio (o/e) 0.95, 90% interval 0.92 to 0.98. Synonymous variants: 1,498 observed, 1,456.7 expected, observed/expected ratio (o/e) 1.03, 90% interval 0.99 to 1.07.
Gene-disease validity (ClinGen):
ClinGen rates the evidence that CFAP46 causes each of these diseases.
primary ciliary dyskinesia (autosomal recessive): Limited. A rare, genetically heterogeneous, primarily respiratory disorder characterized by chronic upper and lower respiratory tract disease.
Homologues: Orthologues: chimpanzee CFAP46 (90% identical), guinea pig CFAP46 (66% identical), rat Cfap46 (62% identical), mouse Cfap46 (62% identical), pig CFAP46 (62% identical), tropical clawed frog cfap46 (40% identical), macaque CFAP46 (13% identical).
Diseases named in the same sentence as CFAP46 in open-access papers:
CFAP46 is named in the same sentence as 12 diseases in open-access papers, as found by Europe PMC text mining. Sharing a sentence is not in itself a finding about the gene and the disease. The quoted sentences say what the papers report.
acute myeloid leukemia (1 paper, 2018). Acute myeloid leukemia (AML) is a group of neoplasms arising from precursor cells committed to the myeloid cell-line differentiation. "TTC40 encodes cilia and flagella associated protein 46, which is reported to play a role in the occurrence of nasopharyngeal carcinoma and acute myeloid leukemia." (PMID 29843777, 2018).
anxiety disorder (1 paper, 2021). A category of psychiatric disorders which are characterized by anxious feelings or fear often accompanied by physical symptoms associated with anxiety. "The stress environmental factors like early life adversity would trigger the DNA methylation change (Provençal and Binder, 2015), and epigenome-wide association study (EWAS) have reported many genes that showed epigenetic changes in anxiety disorders, including CFAP46, SLC43A2, and TNXB." (PMID 34650599, 2021).
breast carcinoma (1 paper, 2024). "On the other hand, although CFAP46 role in breast cancer is not yet clear, gene fusion involving various other genes such as VTI1A (reported to cause the initiation of glioma and other cancers) has been reported to play a role in breast cancer." (PMID 39723380, 2024).
ciliopathy (1 paper, 2022). A genetic disorder of the cellular cilia or the cilia anchoring structures, the basal bodies, or of ciliary function. "CFAP54, NME8, and CFAP46 are ciliopathy-related genes that strongly increase the risk of respiratory infections due to the inability to remove inhaled pathogens, including SARS-CoV-2." (PMID 36552859, 2022).
influenza infection (1 paper, 2023). "Nonetheless, the WDR93 and CFAP46 gene disruption patterns suggest their loss could have functional significance for influenza infection." (PMID 37621660, 2023).
lung diseases (1 paper, 2024). "CFAP46 has also been reported to be associated with airway and lung diseases by modulating inflammatory responses." (PMID 38396057, 2024).
panic disorder (1 paper, 2022). An anxiety disorder characterized by multiple unexpected panic attacks with persistent concern of recurring attacks. "In several EWAS studies of panic disorder, it was found that 40 CpG loci were significantly associated with hypo-methylation, gender-specific methylation changes may exist in HECA gene, and the degree of cg19917903 methylation in CFAP46 gene decreased significantly." (PMID 36032246, 2022).
CFAP46 also shares sentences with these, for which no sentence is quoted: cancer (2 papers); colon cancer (1); glioma (1); nasopharyngeal carcinoma (1); respiratory infections (1).